TAS2R16 (taste 2 receptor member 16)
Description:
Gustducin-coupled receptor implicated in the perception of bitter compounds in the oral cavity and the gastrointestinal tract. Signals through PLCB2 and the calcium-regulated cation channel TRPM5.
Synonyms: T2R16; BGLPT
Tractability: Antibody: UniProt places it where antibodies can reach, with high confidence; its Gene Ontology location is reachable by antibodies, with high confidence; UniProt predicts a signal peptide or a membrane-spanning region. PROTAC: a small molecule that binds it is known.
Target class: Membrane receptor; Taste receptor (taste family GPCR); Taste family G protein-coupled receptor
Safety:
Unwanted effects reported when the protein is acted on. In parentheses: how it was acted on, where the effect was seen, and who reports it.
become addicted to alcohol (source: ClinPGx)
Gene: Protein-coding gene on chromosome 7 (122,994,704 to 122,995,700, reverse strand). Ensembl gene ENSG00000128519.
Subcellular location: Cell membrane
Pathways (Reactome):
Signal Transduction: Class C/3 (Metabotropic glutamate/pheromone receptors); G alpha (i) signalling events
Sensory Perception: Sensory perception of sweet, bitter, and umami (glutamate) taste
Gene Ontology:
Molecular function: bitter taste receptor activity; protein binding; G protein-coupled receptor activity
Biological process: detection of chemical stimulus involved in sensory perception of bitter taste; G protein-coupled receptor signaling pathway; sensory perception of taste
Cellular component: endoplasmic reticulum; external side of plasma membrane; plasma membrane; trans-Golgi network; membrane
Genetic constraint (gnomAD): Loss-of-function variants: 5 observed, 4.15 expected, observed/expected ratio (o/e) 1.2, 90% interval 0.6 to 1.89. That is too few expected variants to judge how well the gene tolerates losing a copy. Missense variants: 281 observed, 282.28 expected, observed/expected ratio (o/e) 1, 90% interval 0.9 to 1.1. Synonymous variants: 112 observed, 101.77 expected, observed/expected ratio (o/e) 1.1, 90% interval 0.94 to 1.29.
Homologues: Orthologues: chimpanzee TAS2R16 (99% identical), macaque TAS2R16 (90% identical), rabbit TAS2R16 (64% identical), pig TAS2R16 (62% identical), guinea pig TAS2R16 (55% identical), mouse Tas2r118 (53% identical), rat Tas2r118 (52% identical), tropical clawed frog t2r13 (23% identical), tropical clawed frog tas2r7 (22% identical), tropical clawed frog tas2r4 (21% identical), tropical clawed frog t2r3 (20% identical), tropical clawed frog t2r8 (20% identical), and 9 more. Paralogues in human: TAS2R41 (35% identical), TAS2R60 (31% identical), TAS2R9 (27% identical), TAS2R3 (26% identical), TAS2R7 (25% identical), TAS2R1 (25% identical), TAS2R50 (25% identical), TAS2R14 (25% identical), TAS2R46 (25% identical), TAS2R8 (25% identical), TAS2R20 (24% identical), TAS2R39 (24% identical), and 11 more.
Diseases named in the same sentence as TAS2R16 in open-access papers:
TAS2R16 is named in the same sentence as 25 diseases in open-access papers, as found by Europe PMC text mining. Sharing a sentence is not in itself a finding about the gene and the disease. The quoted sentences say what the papers report.
colorectal adenoma (4 papers, 2017 to 2024). An adenoma that arises from the colon or rectum. "Schembre and their research team conducted a study investigating two TAS2R16 polymorphic variants (rs846672 and rs846664) concerning the risk of developing colorectal adenoma." (PMID 38673029, 2024). "Schembre and colleagues have performed a study investigating two TAS2R16 polymorphic variants (rs846672 and rs846664) in relation to the risk of developing colorectal adenoma." (PMID 28915899, 2017). "In contrast, in a multi-ethnic case–control study, neither the risk for developing colorectal adenoma nor most selected dietary variables were associated with several genetic variations of the bitter taste receptor genes TAS2R16, TAS2R38 and TAS2R50." (PMID 34885005, 2021). "In a cohort study of colorectal adenoma cases, researchers explored the association between colorectal adenoma risk, dietary intake and genetic variation in three TAS2R genes: TAS2R38 (rs713598, rs1726866, rs10246939), TAS2R16 (rs846672) and TAS2R50 (rs1376251)." (PMID 32708215, 2020).
colon cancer (3 papers, 2017 to 2024). "One of the risk factors for both colon cancer and PA is known to be heavy alcohol consumption, which is influenced by TAS2R16 genetic variations associated with alcohol dependence." (PMID 39335536, 2024). "A recent study examined the association of TAS2R16 single-nucleotide variants (SNVs) with colon cancer, as polymorphic variants of this gene have been shown to increase alcohol dependence." (PMID 39335536, 2024). "Our data suggest that polymorphisms within TAS2R16 gene do not have a strong influence on colon cancer susceptibility, but a possible role in rectal cancer should be further evaluated in larger cohorts." (PMID 28915899, 2017).
colorectal cancer (3 papers, 2017 to 2024). A primary or metastatic malignant neoplasm that affects the colon or rectum. "For example, in 2017, Barontini and co-authors studied the associations of TAS2R16 rs860170, rs978739, rs1357949, rs1525489, rs6466849, rs10268496 gene polymorphisms with colorectal cancer." (PMID 38673029, 2024).
rectal cancer (3 papers, 2017 to 2024). A primary or metastatic malignant neoplasm that affects the rectum. "For example, another TAS2R16 variant (rs1525489) was investigated in a study by Barontini and co-authors, whose C allele was associated with an increased risk of rectal cancer (p = 0.047)." (PMID 39335536, 2024). "We can hypothesize that TAS2R16 genetic variants may influence the occurrence of PA, as they are associated with the development of rectal cancer." (PMID 39335536, 2024). "However, one of the six investigated SNPs in TAS2R16 showed a weakly positive association with the risk for developing rectal cancer (OR—1.62; 95% CI—(1.06, 2.47); p = 0.03)." (PMID 34885005, 2021). "Other researchers investigated the relationship between TAS2R16 rs860170 and colon and rectal cancers." (PMID 39335536, 2024).
neuroblastoma (2 papers, 2023 to 2024). Neuroblastoma (NB) is the most common solid, extracranial childhood tumor. "Not only that TAS2R16 induced neurite outgrowth in the human neuroblastoma cells via the ERK pathway." (PMID 37799274, 2023).
periodontitis (2 papers, 2021 to 2024). An acute or chronic inflammatory process that affects the tissues that surround and support the teeth. "Females carrying the TAS2R16 rs978739 C allele demonstrated a higher susceptibility to the development of generalized periodontitis." (PMID 38397921, 2024). "Associations were found between TAS2R16 rs860170 polymorphisms, elevated TAS2R16 serum levels, and generalized periodontitis development." (PMID 38397921, 2024). "The study examined TAS2R16 gene variants in individuals with generalised periodontitis, yielding significant insights into the genetic foundation and development of this complex disease." (PMID 38397921, 2024). "Females carrying the TAS2R16 rs978739 C allele were more prone to generalized periodontitis development." (PMID 38397921, 2024). "The aim of this research was to analyse the TAS2R16 serum levels and common gene rs860170, rs978739, and rs1357949 polymorphisms in patients affected by generalized periodontitis." (PMID 38397921, 2024). "Significant correlations were observed between the presence of TAS2R16 rs860170 polymorphisms, increased TAS2R16 serum levels, and the onset of generalized periodontitis." (PMID 38397921, 2024). "The objective of this study was to evaluate and compare the associations between TAS2R16 serum levels and common gene rs860170, rs978739, and rs1357949 polymorphisms in patients affected by generalized periodontitis." (PMID 38397921, 2024). "Further studies focusing on TAS2R16 gene polymorphisms and their potential association with periodontitis are essential to enhance our understanding of the genetic basis of this complex disease." (PMID 38397921, 2024). "In this study, we aimed to analyse the association between TAS2R16 rs860170, rs978739, and rs1357949 polymorphisms and TAS2R16 serum levels and patients affected by generalized periodontitis, in comparison to a control group of healthy subjects." (PMID 38397921, 2024). "It is imperative to conduct future research and undertake a thorough analysis of the potential correlation between polymorphisms in the TAS2R16 gene and the occurrence of periodontitis." (PMID 38397921, 2024). "TAS2R16 rs860170 (TT, CT, and CC) showed a statistically significant difference between males in generalized periodontitis and reference groups (38.4%, 61.6%, and 0% vs. 32.9%, 56.6%, and 10.5%, p = 0.002)." (PMID 38397921, 2024). "The analysis of TAS2R16 rs860170 (TT, CT, and CC) showed a statistically significant difference between generalized periodontitis and the reference group (41.8%, 58.2%, and 0% vs. 38.7%, 56.1%, and 5.2%, p < 0.001)." (PMID 38397921, 2024). "Subjects aged 70 years and older demonstrated a statistically significant difference in TAS2R16 rs860170 (TT, CT, and CC) between generalized periodontitis and the reference group (42.8%, 57.2%, and 0% vs. 38.6%, 53.8%, and 7.6%, p = 0.003)." (PMID 38397921, 2024). "Since the activation of TAS2R16 suppresses the inflammatory response in human gingival fibroblasts (HGFs), TAS2Rs could serve as a promising target for the treatment of periodontitis." (PMID 38397921, 2024). "Genotyping of TAS2R16 (rs860170, rs978739, and rs1357949) was performed using real-time polymerase chain reaction (RT-PCR), and serum level analysis was performed for both periodontitis-affected patients and reference group subjects." (PMID 38397921, 2024). "Given that TAS2R16 activation inhibited the inflammatory response in HGFs, TAS2Rs may be exploited as a potential target for the treatment of periodontitis." (PMID 34975834, 2021).
brain tumors (1 paper, 2024). "Currently, there is limited research on TAS2R16 in CNS diseases and brain tumors, particularly in PA." (PMID 39335536, 2024).
gout (1 paper, 2016). A condition characterized by painful swelling of the joints, which is caused by deposition of urate crystals. "However probenecid is not a selective inhibitor for specific bitter taste receptors (TAS2R16, -38 and -43), it inhibits also organic anion transporters (OAT1) and is clinically approved for the treatment of gout." (PMID 26950109, 2016).
helminth infection (1 paper, 2021). "Similar to the tissue sampled post-helminth infection, probes to IL17RB, TAS2R16 and DCLK-2 co-localized with POU2F3 probe, but in a lower number of cells, as expected from our IHC data." (PMID 34880874, 2021).
multiple sclerosis (1 paper, 2024). A progressive autoimmune disorder affecting the central nervous system resulting in demyelination. "The study aimed to investigate the association between the TAS2R16 gene (rs860170, rs978739, rs1357949), TAS2R16 serum levels, and multiple sclerosis (MS)." (PMID 38673029, 2024).
nematode infection (1 paper, 2021). "Taste receptor TAS2R16, adhesion receptor ADGRG6 (GPR126) and orphan receptor GPRC5C were enriched in abomasal tuft cells, and our data suggest these may be the main receptors involved in sensing nematode infection in the abomasum." (PMID 34880874, 2021).
nicotine dependence (1 paper, 2012). Physical and psychological dependence on nicotine. "TAS2R16 genetic variants have also been associated with the development of nicotine dependence in African Americans." (PMID 23133589, 2012).
periodontal diseases (1 paper, 2024). "Although no scientific literature describing TAS2R16 (rs860170, rs978739, and rs1357949) polymorphisms in association with periodontal diseases was found, numerous extra-gustatory tissues, including the respiratory tract, gastrointestinal mucosa, and gingiva, have been shown to express TAS2Rs." (PMID 38397921, 2024).
Pituitary Adenoma (1 paper, 2024). "The TAS2R16 gene codes for a taste receptor and is involved in bitter taste perception, but there is currently no known direct link between this gene and pituitary adenoma." (PMID 39335536, 2024).
neoplasia (3 papers, 2017 to 2024). "Given the importance of inflammation in CRC, we tested whether polymorphic variants in this gene could affect the risk of developing this neoplasia hypothesizing a role of TAS2R16 in modulating chronic inflammation within the gut." (PMID 28915899, 2017). "TAS2R16 can influence the tumor microenvironment due to its expression in various immune cells, including macrophages and dendritic cells." (PMID 39335536, 2024). "In these cells, TAS2R16 can affect their activation state and function, thereby contributing to angiogenesis, tumor growth, and immune suppression." (PMID 39335536, 2024). "TAS2R16 could contribute to the inflammatory environment that sometimes accompanies PA, potentially affecting tumor growth or the body’s response to the tumor." (PMID 39335536, 2024). "TAS2R16 represents a promising target in PA development due to its potential roles in regulating cell proliferation, apoptosis, immune responses, and inflammation within the tumor microenvironment." (PMID 39335536, 2024). "Moreover, other research suggests that taste receptors, including TAS2R16, may also have roles in various non-taste-related biological processes, including cell proliferation and tumor growth." (PMID 39335536, 2024).
cancer (2 papers, 2017 to 2024). A tumor composed of atypical neoplastic, often pleomorphic cells that invade other tissues. "Since TAS2R16 is involved in inflammatory processes, it could help modulate the chronic inflammation often associated with cancer progression." (PMID 39335536, 2024). "It was also identified that activation of certain taste receptors, including TAS2R16, can induce apoptosis in cancer cells." (PMID 39335536, 2024).
TAS2R16 also shares sentences with these, for which no sentence is quoted: alcohol dependence (2 papers); autism spectrum disorder (1); autoimmune disease (1); dental caries (1); exudative vitreoretinopathy (1); hyperlysinemia (1); infection (1); oral diseases (1); upper respiratory infections (1).